SLC5A11 (solute carrier family 5 member 11)
Description:
Involved in the sodium-dependent cotransport of myo-inositol (MI) with a Na(+):MI stoichiometry of 2:1. Exclusively responsible for apical MI transport and absorption in intestine (By similarity). Can also transport D-chiro-inositol (DCI) but not L-fucose. Exhibits stereospecific cotransport of both D-glucose and D-xylose (By similarity). May induce apoptosis through the TNF, PDCD1 pathway. May play a role in the regulation of MI concentration in serum, involving reabsorption in at least the proximal tubule of the kidney (By similarity).
Synonyms: SMIT2; KST1; SGLT6; RKST1
Tractability: Small molecule: it belongs to a druggable protein family. Antibody: its Gene Ontology location is reachable by antibodies, with high confidence; UniProt places it where antibodies can reach, with medium confidence; UniProt predicts a signal peptide or a membrane-spanning region. PROTAC: a small molecule that binds it is known.
Target class: SLC superfamily of solute carriers; SLC05 family of sodium-dependent glucose transporters; Electrochemical transporter; Transporter
Gene: Protein-coding gene on chromosome 16 (24,845,841 to 24,911,628, forward strand). Ensembl gene ENSG00000158865.
Subcellular location: Membrane; Apical cell membrane
Subcellular location (Human Protein Atlas): Nucleoplasm; Cytosol
Pathways (Reactome):
Transport of small molecules: Inositol transporters
Gene Ontology:
Molecular function: myo-inositol transmembrane transporter activity; protein binding; D-glucose:sodium symporter activity; polyol transmembrane transporter activity; transmembrane transporter activity
Biological process: myo-inositol transport; carbohydrate transmembrane transport; hexose transmembrane transport; polyol transmembrane transport; sodium ion transmembrane transport; transmembrane transport
Cellular component: apical plasma membrane; plasma membrane; membrane
Genetic constraint (gnomAD): Loss-of-function variants: 45 observed, 68.78 expected, observed/expected ratio (o/e) 0.65, 90% interval 0.51 to 0.84. The upper end of that interval is the gene's LOEUF score, 0.84, which puts it in group 3 of 6, group 1 being the genes least tolerant of losing a copy. Missense variants: 756 observed, 872.31 expected, observed/expected ratio (o/e) 0.87, 90% interval 0.82 to 0.92. Synonymous variants: 307 observed, 347.71 expected, observed/expected ratio (o/e) 0.88, 90% interval 0.8 to 0.97.
Homologues: Orthologues: macaque SLC5A11 (97% identical), chimpanzee SLC5A11 (94% identical), pig SLC5A11 (89% identical), dog SLC5A11 (88% identical), rat Slc5a11 (87% identical), guinea pig SLC5A11 (87% identical), mouse Slc5a11 (86% identical), rabbit SLC5A11 (84% identical), tropical clawed frog slc5a11 (68% identical), zebrafish slc5a11 (62% identical), Drosophila melanogaster CG31668 (17% identical), Drosophila melanogaster rumpel (16% identical), and 8 more. Paralogues in human: SLC5A1 (51% identical), SLC5A9 (49% identical), SLC5A4 (49% identical), SLC5A2 (49% identical), SLC5A3 (47% identical), SLC5A10 (46% identical), SLC5A12 (22% identical), SLC5A6 (20% identical), SLC5A5 (20% identical), SLC5A8 (20% identical), SLC5A7 (15% identical).
Diseases named in the same sentence as SLC5A11 in open-access papers:
SLC5A11 is named in the same sentence as 14 diseases in open-access papers, as found by Europe PMC text mining. Sharing a sentence is not in itself a finding about the gene and the disease. The quoted sentences say what the papers report.
Obesity (2 papers, 2021 to 2022). Accumulation of substantial excess body fat. "We found mQTLs for the cg06028605 site within the SLC5A11 gene overlap with obesity risk SNPs (PSMR = 2.6 × 10−10, PHEIDI = 0.3)." (PMID 34207686, 2021). "MR analysis revealed that this site contributes to the risk of obesity by changing the expression of the SLC5A11 gene." (PMID 34207686, 2021). "We noted that the lower methylation at the cg06028605 site in the SLC5A11 locus contributes to obesity by decreasing the expression of this gene." (PMID 34207686, 2021).
autoimmune disease (1 paper, 2022). A disorder resulting from loss of function or tissue destruction of an organ or multiple organs, arising from humoral or cellular immune responses of the individual to their own tissue constituents. "SLC5A11, encoding SGLT6, may play a role in human autoimmune diseases by interacting with immune genes." (PMID 35663316, 2022).
breast carcinoma (1 paper, 2020). "In contrast, SLC5A11, SLC6A4 and MRPS12 were the most downregulated in HIV-positive breast cancer with a long2foldchange of −6.7, 6.5 and −4.7, respectively." (PMID 33194615, 2020).
sarcoma (1 paper, 2015). A usually aggressive malignant neoplasm of the soft tissue or bone. "Although the fusion partner, SLC5A11, is distinct from that observed in sarcomas, it is likely that this fusion has transforming potential in ATCs." (PMID 26680454, 2015).
systemic lupus erythematosus (1 paper, 2016). An autoimmune multi-organ disease typically associated with vasculopathy and autoantibody production. "Markers in the SLC5A11 gene have been implicated in systemic lupus erythematosus (SLE) susceptibility." (PMID 27355821, 2016).
tumor (2 papers, 2015 to 2021). "PNA-A15 treatment upregulated A-T repeat-containing genes that act as tumour suppressor genes, such as BAHD1, CCAR1, EGR1, and SLC5A11." (PMID 34059086, 2021).
SLC5A11 also shares sentences with these, for which no sentence is quoted: diabetes mellitus (2 papers); Alzheimer disease (1); cancer (1); genetic diseases (1); Hyperglycemia (1); Hypertension (1); melanoma (1); synovial sarcoma (1).